VTN (vitronectin)
Diseases named in the same sentence as VTN in open-access papers (continued):
Sharing a sentence is not in itself a finding about the gene and the disease.
tumor (continued). "The ECM is a major structural component of the tumor microenvironment, and FN1 and VTN are part of the group of glycoproteins that make the ECM a cohesive network linking cells together with other structural components." (PMID 35477343, 2022). "However, upanap-126 significantly affected tumor cell intravasation and dissemination in vivo due to the inhibition of pro-uPA activation, competing with the binding of pro-uPA to uPAR and preventing the binding of the pro-uPAR/uPAR complex to the glycoprotein vitronectin." (PMID 35563278, 2022). "Expression of COL6A1-A3 and FN1 was high both in primary tumor and metastatic tissues, pre- and post-chemotherapy, while COL6A5-A6 and VTN expression was lower (primary tumor pre-chemo n = 32/post-chemo n = 13; metastatic tissues n = 55/n = 38)." (PMID 34162871, 2021). "It is obvious that omental stroma cells are the main producers of most collagens and, together with tumour cells, other ECM components (fibronectin, laminins, vitronectin)." (PMID 34841720, 2021). "VTN (vitronectin), as a cell-adhesion glycoprotein, is primarily localized in the ECM (extracellular matrix) and provides the facility to help tumor cells to breach through to the basement membrane in the process of cancer cell invasion." (PMID 30819137, 2019). "Integrins can bind to fibronectin, vitronectin, laminin, and collagen in the ECM, thereby enhancing tumor cell motility and invasion ability." (PMID 31234517, 2019). "Vitronectin-bound PAI-1 reducesthe interaction of vitronectin with integrins on the surface of TSCs and,thereby, promotes the release of TSCs from tumor niches, regulating theiradhesion and migration." (PMID 30713759, 2018). "In the present study, we demonstrated that SNCG, as a secreted protein, also controlled secretion of many proteins in the tumor microenvironment, including ECM proteins such as fibronectin, vitronectin, the MMPs like MMP-2 and MMP-24." (PMID 29903032, 2018). "We show that mast cells secrete increased amounts of granzyme b upon therapy, which mobilizes pro-angiogenic laminin- and vitronectin-bound FGF-1 and GM-CSF from the tumor matrix." (PMID 28814715, 2017). "In the present study, we localized vitronectin staining in NSCLC tumors to the stroma surrounding blood vessels and to restricted areas of the tumor-stromal interface." (PMID 27484721, 2016). "Thus, soluble vitronectin can act to direct migration and to stimulate general motility of lymphocytes, and this response may be further stimulated when the lymphocyte interacts with immobilised vitronectin in the tumour stroma." (PMID 17088900, 2006). "Tumour-infiltrating lymphocytes from both CHM and HCC showed significant chemotactic responses to vitronectin, which peaked between 0.2 and 20 ng ml−1." (PMID 17088900, 2006). "Thus, vitronectin may promote the accumulation of lymphocytes within the tumour stroma." (PMID 17088900, 2006). "As reported, FN, laminin, collagen-IV and -I, decorin, tenascin and vitronectin are ECM proteins produced and secreted by cells of malignant tumours of glial origin in vitro and in vivo." (PMID 14647148, 2003). "In a few tumours, collagen type III, vitronectin and undulin were expressed on the luminal side of the neoplastic glands, suggesting loss of normal polar differentiation." (PMID 8286197, 1994). "Additionally, tumor size categorization showed significantly fewer tumors measuring 2–4 mm and over 4 mm in the CAF‐specific VTN knockout group." (PMID 40538300, 2025). "Meanwhile, integrin αvβ5 promotes VM formation by binding to vitronectin in the ECM and activating the FAK signaling pathways, which subsequently upregulate VEGFA and MMP9 expression, enhancing tumor cell migration, invasion, and the formation of tubular VM structures." (PMID 41019994, 2025). "Of note, tumour cells showed a very high binding activity to vitronectin also in the absence of β6 expression." (PMID 40488391, 2025).
tumor (continued). "The VTN, CypA, and VEGF signalling pathways were significantly activated in these subpopulations, underscoring the enhanced invasiveness and angiogenic capacity of these tumour cells." (PMID 39944086, 2025). "Importantly, the CT26+NIH3T3‐LV‐VTN group demonstrated a 12.93% lower tumor suppression rate than the CT26+NIH3T3‐LV‐VEC group, indicating a relative resistance of VTN‐expressing tumors to aPD1 therapy in CRC." (PMID 40538300, 2025). "Vitronectin/mTOR; IL-8/PI3K/Akt/NF-κB promotes tumor metastasis." (PMID 41294885, 2025). "Additionally, an examination of M2‐TAMs in tumor tissues co‐injected subcutaneously with CT26 cells and NIH3T3(LV‐VEC/LV‐VTN) cells indicated elevated F4/80 and CD206 expression in the VTN overexpression group." (PMID 40538300, 2025). "Our studies have shown that VTN secreted by CAFs not only enhances the proliferation and invasion of CRC cells but also facilitates M2 macrophage polarization, intensifying the immunosuppressive TME and accelerating tumor progression." (PMID 40538300, 2025). "Moreover, the ligand-receptor signaling differences between HCC and normal samples showed that pathways such as SPP1, LAMININ and VTN were more prevalent in the HCC microenvironment, suggesting enhanced tumor growth, invasion, and immune evasion." (PMID 40612108, 2025). "Vitronectin (VTN) is a type of secreted glycoprotein composed of 459 amino acids, which participates in the formation of extracellular matrix (ECM) and exhibits high expression in various tumor tissues." (PMID 39717749, 2024). "PAI-1 binds to a variety of protein, such as PA, VTN and LRP1 by changing conformation states, and most of the PAI-1 complex could promote tumor metastasis 11,13,18." (PMID 36605486, 2023). "The expression of collagen I, fibrinogen, elastin, fibronectin, and vitronectin in tumor tissues from patients with the recurrent and non-recurrent disease was determined using immunohistochemistry." (PMID 37369642, 2023). "A proteomic analysis of colorectal normal and tumor ECM revealed that collagen IV, V and XIV, fibrilin, emilin, vitronectin, laminin and endomucin have increased expression in tumor ECM, and that periostin, versican, thrombospondin-2 and tenascin were exclusively present in tumor tissue." (PMID 35053521, 2022). "The ECM glycoprotein vitronectin (VN) is an adhesive molecule that presents multiple binding domains; this allows VN to interact with different ECM molecules and integrins, which have been shown to promote tumor cell migration." (PMID 36425532, 2022). "Once the tumor cells break away from the constraint of ECM networks, they would move toward the stimuli along with the ECM fiber by interacting with other ECM components, such as fibronectin and vitronectin." (PMID 31300030, 2019). "Among the proteins from tumor stroma, the protein ITGAV is a receptor of ECM and serves as a subunit for receptors of integrins, RGD-motif bound containing substrates, such as vitronectin, fibronectin and fibrinogen, which are components of the stroma involved in the EMT transition." (PMID 30185791, 2018). "This leads to the intriguing possibility that cells engaging vitronectin may activate FRA-1 through increased phosphorylation and result in increased tumor cell extravasation." (PMID 29382358, 2018). "Vitronectin is a possible candidate as it is expressed at the leading edge of the tumour but is unlikely to be the only one, as we found, it is only expressed in 20 % of our samples." (PMID 27541285, 2017). "Several studies found both hypoxia and vitronectin may induce the recruitment of integrin αvβ3 to cell membrane of GBM cells, thereby activating the focal adhesion kinase (FAK) to promote tumor invasion." (PMID 26717039, 2016). "First, it most likely plays an important role in vivo in the egress of cells from a primary tumor into the interstitial fluid, where vitronectin is present and not chaperoned by fibrinogen." (PMID 27634880, 2016).
tumor (continued). "Additionally, we detected vitronectin, the ligand for integrin αvβ5, in human NSCLC tumors surrounding blood vessels and in the interstitium between the tumor and stroma." (PMID 27484721, 2016). "In CHM, vitronectin was absent from vessels and αvβ3 was detected on tumour endothelium but not on TIL." (PMID 17088900, 2006). "Soluble vitronectin-induced dose-dependent migration of TIL in in vitro chemotaxis and haptotaxis assays and vitronectin in tissue sections was able to support TIL adhesion to tumour stroma." (PMID 17088900, 2006). "Analysis of TIL adhesion to noninvolved tissue surrounding the tumour revealed that vitronectin supported adhesion to portal tracts where vitronectin expression was confined." (PMID 17088900, 2006). "Lymphocytes were freshly isolated from tumours, rested overnight and either used without further stimulation or expanded in IL-2 before testing their ability to migrate towards soluble vitronectin in chemotaxis assays." (PMID 17088900, 2006). "In HCC, sinusoidal-type vessels were positive for vitronectin and αvβ3 was detected on tumour vessels but not on CD2+ lymphocytes." (PMID 17088900, 2006). "Among these genes are ERBB2, CCNA1, FOXC2, LEFTY2, VTN, ACKR3, and PTGS2, which influence processes such as apoptosis, epithelial–mesenchymal transition, angiogenesis, hypoxia responses, and KRAS signaling pathways, all vital for tumor aggressiveness and metastatic spread." (PMID 39000413, 2024). "These genes, including ERBB2, CCNA1, FOXC2, LEFTY2, VTN, ACKR3, and PTGS2, are involved in key processes like apoptosis, epithelial–mesenchymal transition, angiogenesis, response to hypoxia, and KRAS signaling pathways, which are crucial for tumor virulence and the spread of metastases." (PMID 39000413, 2024). "We also verified that MEF2C affects the adhesion of tumor cells to the extracellular matrix by cell adhesion assays.The results showed that the adhesion of si-MEF2C cells to the extracellular matrix such as vitronectin and fibronectin was reduced compared with the control group." (PMID 36059448, 2022). "Moreover, it inhibits tumor growth and angiogenesis as it can bind to different proteins such as growth factors and cytokines like FGF, VEGF, PF4, IL8, and adhesion proteins such as vitronectin, fibronectin, selectins, and integrins." (PMID 34440575, 2021). "Besides the remodeling of the collagen fiber network of tumor stroma around the tumor mass, some ECM molecules, such as hyaluronan (HA), proteoglycans, and glycoproteins (e.g., fibrin, fibronectin and vitronectin), are upregulated and become able to biologically affect stroma cells." (PMID 30736469, 2019). "Moreover, the treatment significantly reduced expression levels of EGFRvIII, integrin αvβ3, VTN, as well as the cellular distributions of integrin β3, αv in non-necrotic area of the tumor mass in vivo in EGFRvIII-xenografts." (PMID 26717039, 2016). "Tumour-infiltrating lymphocytes showed increased migration to immobilised vitronectin compared with BSA control, although there was no increase with the higher coating concentration, suggesting that 0.02 μg ml−1 is sufficient for optimal coating of the chemotaxis membranes." (PMID 17088900, 2006). "Also, some studies have reported that uPAR could activate cellular signaling and increase tumor cell malignancy in the absence of uPA through the binding of vitronectin." (PMID 27602956, 2016). "Vitronectin is absent in the normal colon, but appears to be expressed in CRC, possibly by induction of the surrounding fibroblasts by the tumor cells." (PMID 26243458, 2016).
cancer (95 papers, 2006 to 2025). A tumor composed of atypical neoplastic, often pleomorphic cells that invade other tissues. "High vitronectin (VN) expression has been associated with poor prognosis in other cancers, and we aimed to determine the utility of this extracellular matrix glycoprotein as a biomarker of aggressiveness in ES." (PMID 39409975, 2024). "Unlike PAI-1, elevated levels of PAI-2 in cancer are linked with reduced cancer progression and metastasis due to its inability to bind to vitronectin." (PMID 35008762, 2021). "In this study, primary human CAFs and NFs were isolated and subjected to a series of in vivo and in vitro experiments to elucidate the pro‐cancer effects of VTN in CRC." (PMID 40538300, 2025). "CR clots exhibited high levels of proteins associated with active cancer and immune responses, such as IGHG1 and VTN." (PMID 40079446, 2025). "Further analysis of ligand-receptor pairs revealed that VTN-(ITGAV + ITGB5), SEMA4D-PLXNB2, GAS6-TYRO3, and FN1-(ITGA3 + ITGB1) were more prevalent in high-risk cancer cells." (PMID 41034991, 2025). "VTN’s role in cancer is concentrated in breast, ovarian, and prostate cancers, and previous studies have shown that it can be used as a serum marker for early cancer detection." (PMID 40433359, 2025). "VTN enhances the adhesion ability of cancer cells to vasculature and tissues, facilitating metastasis and invasion within the body." (PMID 40433359, 2025). "A large body of literature has proven that VTN is pivotal in cancer malignancy by activating cell invasion and metastasis." (PMID 39717749, 2024). "Regarding proteoglycans in cancer (p = 1.08e-03), the vitronectin gene interacted with seven lncRNAs, and XLOC_031636 interacted with five mRNAs." (PMID 38926642, 2024). "We further demonstrated that GALNT12-BMP signaling decreased integrin αVβ3 expression, suppressed the binding of cancer cells to the vitronectin in bone matrix, and thus restrained bone metastasis of PCa." (PMID 38385080, 2024). "The secretome analysis of cancer cells post NVA-IT treatment showed that many proteins like thrombospondin-1, fibronectin, and vitronectin involved in cancer progression, metastasis, and angiogenesis have been affected." (PMID 37900279, 2023). "It has been suggested that it plays a key role in cancer, mainly through its association with urokinase-type plasminogen activator (uPA) and the extracellular matrix (ECM) protein vitronectin." (PMID 36294546, 2022). "Paradoxically, PAI-1, which is expressed by EC during angiogenesis, is elevated in several cancers and is found to promote angiogenesis by regulating plasmin-mediated proteolysis and by promoting cellular migration through vitronectin." (PMID 35008762, 2021). "To validate the clinical relevance of our findings, we first used The Cancer Genome Atlas (TCGA) transcriptomics microarray data of 538 chemo-naïve OC samples to assess survival associations of COL6, FN1, and VTN expression." (PMID 34162871, 2021). "We focused on vitronectin expression levels in various cancers, and found that BC cell lines had higher levels of amplified copy number of vitronectin than any other cancer type." (PMID 33211735, 2020). "Analysis of the data shows that there is difference in vitronectin concentration levels between control groups versus cancer with a p-value 0.0149." (PMID 33211735, 2020). "Increased MMPs cleave the ECM proteins fibronectin and vitronectin present on the surface of the mesothelium into smaller fragments and enhance binding of the cancer cells to these ECMs through cancer cell α5β1-integrin and αvβ3-integrin, respectively." (PMID 32780245, 2020). "After analyzing the CCLE dataset, which consisted of 1739 cancer cell lines (over 20 different types of cancer cell-lines), we determined that about 3% of all cases had its vitronectin copy number is amplified." (PMID 33211735, 2020).
cancer (continued). "The expression of mesenchymal markers associated with cancer progression, such as FN1, VTN, and ITGA5, was markedly increased (between 20- and 50-fold)." (PMID 32699630, 2020). "In physiological conditions, vitronectin is involved in wound healing and homeostasis whereas in PDAC, vitronectin is overexpressed and binds to collagen I, promoting cancer cell migration." (PMID 32984031, 2020). "Serpine1 is a serine protease inhibitor shown to play a role in cancer metastasis through binding of vitronectin leading to detachment of cancer cells from the extracellular matrix." (PMID 31118047, 2019). "The protein composition of the extracellular matrix deposited by cancer cells on the scaffold recapitulated that of the corresponding xenografts, with the exception of vitronectin content that for MCF-7 was markedly higher in vivo." (PMID 31439905, 2019). "Their results suggest that interactions αvβ3-osteopontin, αvβ3-fibronectin and α5β1-fibronectin play a role in HNSCC angiogenesis and interactions α5β1-fibronectin and αvβ5-vitronectin in HNSCC cancer cell behavior." (PMID 30927923, 2019). "This is especially pertinent to proteins such as vitronectin, decorin and fibrinogen and suggests a potential anti-cancer ability of curcumin through suppression of key processes during CCA development." (PMID 30440021, 2018). "It has already been proven that MGP binds to fibronectin and vitronectin and augments cell adhesion and spreading of cancer cells." (PMID 30257426, 2018). "Here we provide evidence for its novel role as a chaperone, preventing vitronectin availability to engage with the uPAR expressed on cancer cells." (PMID 27634880, 2016). "Prior studies support that lysophosphatidic acid is an enhancer of cancer metastasis but in our studies it decreased adhesion to laminin under static and collagen IV, laminin and vitronectin under shear stress." (PMID 26816215, 2016). "Using clinically relevant concentrations of cilengitide in vitro, we observed inhibition of de novo adhesion to and detachment from vitronectin, well-known effects of cilengitide observed in a variety of cancer cell lines." (PMID 27409827, 2016). "Our results presented in this work demonstrate that vitronectin, by engaging the uPAR receptor, is a very potent chemokinetic factor for both cancer cells and normal cells." (PMID 27634880, 2016). "The most important finding of this report is the pro-migratory effect of vitronectin, which directs metastasis of cancer cells to low-fibrinogen environments (e.g., lymphatics or body cavities) in a uPAR-mediated manner." (PMID 27634880, 2016). "Upon increasing the dose, the cancer cell adhesion increased and, in the case of vitronectin, became higher than the control group at early time points." (PMID 26816215, 2016). "In summary, we propose a new explanation for the role of vitronectin in the preferentially egress of cancer cells from tumors, spreading through the lymphatics and metastasizing to body cavities, which are both low in fibrinogen." (PMID 27634880, 2016). "The highly invasive human cancer cells expressing integrin receptor αvβ3 binds to VTN and generates a migratory phenotype through the activation of FAK signaling." (PMID 26068982, 2015). "uPAR-dependent cell adhesion to the ECM protein vitronectin is an important event in wound healing, tissue remodeling, immune response and cancer development." (PMID 25175595, 2014). "Here, we established that P-cadherin is involved in the attachment of cells to ECM substrates, since its silencing rendered cancer cells significantly less able to adhere to vitronectin, fibronectin and laminin." (PMID 24553076, 2014). "Our results of integrin αvβ3 gene expression, which was observed only in stage III EC cells, suggest that vitronectin plays a role in myoinvasion and increases the ability of cancer cells to metastasize." (PMID 25231141, 2014).